ALDH1A3 (aldehyde dehydrogenase 1 family member A3)
Diseases named in the same sentence as ALDH1A3 in open-access papers (continued):
Sharing a sentence is not in itself a finding about the gene and the disease.
cancer (continued). "Among them, the isoform ALDH1A3 is a cancer biomarker since it is highly expressed in cancer stem cells characterized by a marked drug resistance and the capacity to promote self-renewal, clonogenic growth and tumour-initiating capacity." (PMID 33478031, 2021). "The pro-tumorigenic role of ALDH1A3 in cancer is well-described and its utility as a prognostic biomarker is beginning to emerge." (PMID 31974410, 2020). "ALDH1A3 is also important for the survival of other cancer stem-like cells, with effects proposed to be mediated via positive regulation of mitochondrial metabolism." (PMID 35582450, 2020). "Among patients with basal-like cancers, the population co-expressing both PKCλ and ALDH1A3 (43.7%; n = 87/199) was higher than that co-expressing PKCλ and ALDH1A1 (12.1%; n = 24/199)." (PMID 32658903, 2020). "Downregulation of ALDH1A3 sensitized cancer cells, prolonged G1 phase, shortened S phase and decreased cancer cell survival both in vitro and in vivo." (PMID 32111066, 2020). "ALDH1A isozymes are increased in many cancer stem cells, where they contribute to chemoresistance, although it should be noted that there is significant heterogeneity in ALDH1A3 expression in GSC, including within individuals." (PMID 35582450, 2020). "In fact, knockdown of ALDH1A3 expression in vitro models also suppressed cancer cell invasion in different entities." (PMID 32680476, 2020). "ALDH1A3, a member of ALDH1A subfamily, is associated with cancer incidence, progression, prognosis and chemotherapeutic resistance." (PMID 32111066, 2020). "ALDH1A3, also as retinoic acid anabolizing enzyme has been proved a potential novel target for triple-negative breast tumors and cancer stem cells." (PMID 32375698, 2020). "We then analyzed by RT-qPCR the expression of the different markers involved in the cancer stem cells’ biology (Sox2, Oct3/4, Notch1, Nanog, Abcg2, Aldh1a1 and Aldh1a3)." (PMID 32610610, 2020). "ALDH1A3 is also expressed in some cancers, including pancreatic cancer, ovarian cancer and high-grade gliomas." (PMID 32111066, 2020). "And because ALDH1 is a CSC marker in a variety of cancers, we performed Kaplan-Meier and multivariable Cox regression analyses for PKCλ and ALDH1A3 in several cancers." (PMID 32658903, 2020). "Mechanistically, Sox9 acts downstream of Sox2 to control luminal progenitor cell content and is required for expression of the cancer stem cell marker ALDH1A3 and Wnt signalling activity." (PMID 30622340, 2019). "Thereby, it seems that the ALDH1A3 protein is a key inactivator of ROS-generated aldehydes, whose activity determines drug resistance of cancer cells of various origins." (PMID 31413744, 2019). "PALB2, ALDH1A3, and IGF1R were reported to show associations with sensitivity to mitomycin, stem cell markers, and cancer progression, respectively." (PMID 30719229, 2019). "Recent experiments indicate that isoform ALDH1A3 significantly contributes to Aldefluor-positivity in different types of cancer." (PMID 29902974, 2018). "Collectively, these findings indicate that ALDH1A3 play functional roles in both normal and cancer stem/progenitor cells." (PMID 30087899, 2018). "ALDH1A3 labels an aggressive subtype of human PDAC, and patients with ALDH1A3 expression have shorter survival after surgical resection, and inhibition of ALDH1A3 can lead to reduction of cancer cell growth." (PMID 29295482, 2017). "Here, we have investigated the role of ALDH1A3 in cancer progression using ALDH1A3+ and ALDH1A3− GSCs as a model system." (PMID 28423611, 2017). "We found that the well-established cancer stem cell marker Aldh1a3 was highly expressed in Rb-depleted secondary cells, strongly implicating the enrichment of stem cell-like cells in this cell population." (PMID 28099924, 2017). "Efforts to understand the molecular drivers of tTG expression in MES GSCs revealed an unexpected link between tTG and a common marker for stem cells and cancer stem cells, Aldehyde dehydrogenase 1A3 (ALDH1A3)." (PMID 28423611, 2017).
cancer (continued). "We have previously characterized that expression of the cancer stem cell marker ALDH1A3 can have opposing effects in two models of TNBC: it can promote the growth of MDA-MB-231 xenografts while limiting the growth of MDA-MB-468 xenografts." (PMID 29192143, 2017). "Among ALDH1 gene family, isoforms ALDH1A1 and ALDH1A3 are also known as CSCs markers in several cancers." (PMID 28966724, 2017). "Among these targets, we focused on ALDH1A3, a metabolic enzyme that was identified as marker of cancer stem cells." (PMID 27845622, 2016). "The subfamily of aldehyde dehydrogenases 1 (ALDH1) isoenzymes, which comprises ALDH1A1, ALDH1A2, and ALDH1A3, is involved in the synthesis of retinoic acid, and has been identified as functional stem cell markers in diverse cancers." (PMID 27724856, 2016). "ALDH1 has three main isotypes, ALDH1A1, ALDH1A2, and ALDH1A3, and is a marker of normal tissue stem cells (SC) and cancer stem cells (CSC), where it is involved in self-renewal, differentiation and self-protection." (PMID 26783961, 2016). "Surprisingly normal tissue and cancer adjacent tissue showed significantly higher ALDH1A3 intensity compared to the tumor tissues." (PMID 26460734, 2015). "ALDH1A isozymes, mainly ALDH1A1 and ALDH1A3, have been also described as markers of cancer stem cells in different tumors and key determinants for the survival and drug resistance of cancer cells." (PMID 25969992, 2015). "Taxotere and Furtulon also up-regulated some genes (S-100P, ALDH1A3, casein kinase, annexin, etc) responsible for chemotherapeutic resistance, suggesting the induction of cancer cell resistance to these agents." (PMID 15656911, 2005). "Targeting ALDH1A3 thus holds promise for advancing cancer diagnostics and treatment strategies." (PMID 40334012, 2025). "Next, we assessed whether ALDH1A3 affects cell growth across this broad panel of cancer types by testing proliferation for each cell line with and without MBE1.5." (PMID 41210994, 2025). "Interestingly, the paracrine secretion mechanism of ALDH1A3 appears unique to cancer; we have recently demonstrated that ALDH1A3 is responsible for activating cell-autonomous retinoid pathway activation in failing pancreatic β cells." (PMID 41210994, 2025). "Selective inhibition of ALDH1A3 is particularly important, as it may disrupt critical survival mechanisms in cancer cells, enhance tumour sensitivity to standard treatments, and limit the ability of CSCs to drive recurrence." (PMID 40887554, 2025). "One of the imidazopyridine compounds from the same research group (NR6, PDB code: 7A6Q) was further presented as a highly potent and selective ALDH1A3 inhibitor, and was shown to induce cytotoxic effects and reduction in cell migration and stemness of ALDH1A3-positive cancer cells." (PMID 40887554, 2025). "In parallel, while ALDH1A3 has long been shown to be associated with worse outcomes in patients with cancer, its role in retinoid signaling in human tumors has not been conclusively established to date." (PMID 41210994, 2025). "Notably, ALDH1A3 has emerged as a key metabolic target in cancer diagnosis and therapy, as metabolic reprogramming is central to cancer initiation, metastasis, and recurrence." (PMID 40334012, 2025). "Aldehyde dehydrogenase 1A3 (ALDH1A3) is a cancer stem cell marker that promotes metastasis." (PMID 37753740, 2024). "Inhibitors of ALDH1A3 may be valuable in developing new therapies for patients with cancer, obesity, diabetes, and cardiovascular disorders." (PMID 39001459, 2024). "Next, to test the phenotypic response to altering ALDH1A3 and TFAP2B, we found that ALDH1A3 KO led to decreased colony formation while ALDH1A3 OE increased colony formation in both A375 and C089, consistent with the pan-cancer effect of ALDH activity in cancer stem-like states." (PMID 38963759, 2024). "The ALDH1A3 promoter is often hypermethylated compared to normal tissue in cell lines derived from lung, breast, colon, prostate, and cervical cancers." (PMID 39001459, 2024).
cancer (continued). "Furthermore, we found that MMP1/CCL5/ ALDH1A3, which have been identified as cancer‐promoting genes, were the downstream targets of the CPS1/PC‐PLC/DAG/PKC axis." (PMID 39387452, 2024). "It will be important to investigate these effects of ALDH1A3 EMT-MET in other cancers." (PMID 39251846, 2024). "These positive clinical correlates with ALDH1A3 in a different context suggest that ALDH1A3 effects in cancer could be cellular context-specific and dependent on the presence of other molecular factors." (PMID 36672441, 2023). "Here in, we review the role of ALDH1A3 in normal physiology, cancer, and other diseases." (PMID 36672441, 2023). "Indeed, ALDH1A3 can facilitate cancer progression by promoting tumor growth and metastasis, and these effects are mirrored in vitro assays across multiple cancers." (PMID 36672441, 2023). "Furthermore, ALDH1A3, a significant member of the ALDH family, has been associated with tumorigenesis, progression, and radioresistance in various types of cancer." (PMID 37551838, 2023). "In addition, increasing evidence has revealed a strong connection between ALDH1A3 and radioresistance in distinct types of cancer." (PMID 37551838, 2023). "However, aldehyde dehydrogenase 1A family subunits, including ALDH1A1 and ALDH1A3, are highly considered cancer stem cell markers, and their role in maintaining cancer stemness has been explained previously." (PMID 37645246, 2023). "ALDH1A3 upregulation in cancer occurs via multiple mechanisms." (PMID 36672441, 2023). "Given its varied functional roles, it is of no surprise that ALDH1A3 is implicated in multiple cancers and has prognostic relevance." (PMID 36672441, 2023). "Here in, we focus on the specific role of ALDH1A3 in impacting MDR in cancer." (PMID 36672441, 2023). "ALDH1A3 is a well-known cancer stem cell marker in various cancers." (PMID 37686698, 2023). "In addition to glycometabolism, there is evidence that other metabolic pathways are also dysregulated by ALDH1A3 in cancer." (PMID 36672441, 2023). "Although the increased metastasis associated with increased ALDH1A3 could be an indirect result of increased tumor burden and cancer cell proliferation, there is also evidence that ALDH1A3 directly increases the metastatic potential of a cancer cell." (PMID 36672441, 2023). "ALDH1A3 has been reported to play a role in chemoresistance in several types of cancer." (PMID 37551838, 2023). "We discuss its expanding modes of action and the mechanisms of ALDH1A3 regulation in cancer." (PMID 36672441, 2023). "In addition to highlighting the role of ALDH1A3 in the Aldefluor activity of multiple cancers, these studies also demonstrate that when identifying CSCs, detecting the expression of ALDH enzymes is not equal to performing the Aldefluor assay." (PMID 36672441, 2023). "Beyond cancer, we have highlighted the role of ALDH1A3 in other diseases." (PMID 36672441, 2023). "Indeed, this molecule can be considered as the first selective fluorescent probe for human ALDH1A3 ever reported and characterized in a specific cancer cell line." (PMID 36050388, 2022). "Notably, ALDH1A1 and ALDH1A3 are CSCs markers in many tumors and overexpressed in resistant cancer cells." (PMID 35299840, 2022). "In contrast, the level of ALDH1A3 was slightly increased in cancer tissues." (PMID 35280765, 2022). "Studies on the mechanisms of ALDH1A3 in cancer have primarily focused on gene expression changes induced by the enzyme; however, its effects on metabolism have thus far been unstudied and may reveal novel mechanisms of pathogenesis." (PMID 34989902, 2022). "ALDH1A3 is widely distributed in normal tissues and abnormally expressed in a variety of cancers." (PMID 34456632, 2021). "Selectively targeting CSCs through the specific ALDH1A3 inhibition may be a therapeutic winning strategy to hinder invasiveness and stemness of cancer cells and consecutively tumour growth." (PMID 33478031, 2021).
cancer (continued). "One of the ALDH1A member most expressed in several cancer types is ALDH1A3." (PMID 33478031, 2021). "In addition, CPZ was able to downregulate the expression of OCT 3/4, SOX2, NANOG, Nestin, OLIG2 and ALDH1A3, universal cancer stem cells genes for GBM." (PMID 33718225, 2021). "Thus, ALDH1A3 can be a potential marker for cancer diagnosis and therapeutic target, but the mechanism of action remains to be illustrated." (PMID 33419984, 2021). "Using bioinformatics and functional studies, we elucidated that both miR-16-5p and miR-15b-5p targeted ALDH1A3 selectively increased due to CuET treatment, hence could modulate cancer cells growth." (PMID 33419984, 2021). "Similarly, ALDH1A3 knockout in an ALDH1A3 dominant cell line reduced cancer cell viability and significantly restricted cancer initiation and growth." (PMID 33664846, 2021). "Thus, CuET plays an anti-cancer role via selectively targeting specific miRNAs and ALDH1A3 signaling pathway." (PMID 33419984, 2021). "Hence, further research on investigating their cytotoxicity alone and in combination with anticancer drugs in drug-resistant cancer cell lines, particularly those expressing elevated levels of the ALDH1A3 isoform, is worth pursuing." (PMID 34641313, 2021). "Identifying these effectors would delineate the mechanism of ALDH1A3 in cancer." (PMID 31197235, 2020). "Interestingly, siBRCA1 treatment resulted in significant increase in the expression of cancer stem cell-associated markers including CD44, ALDH1A3, and OCT4, while leading to down-regulation of CD24 (p < 0.0001 for all pair-wise comparisons)." (PMID 31273285, 2019). "Additionally, cancer stem cell markers were also overexpressed in N1b PTMC (ALDH1A3: 4.9‐fold, TM4SF1: 7.6‐fold, and PROM1: 5.4‐fold) (all P < .001)." (PMID 31498560, 2019). "Several studies showed that ALDH1A3 is a cancer stem cell gene." (PMID 30087899, 2018). "In addition to these, other cancer stemness associated genes including EPCAM (1.6 folds), ALDH2 (1.3 folds), ALDH1A3 (0.9 folds) and HIF1A (0.7 folds) are all found up-regulated though to less extent." (PMID 28698547, 2017). "Among the ALDH1 family subtypes, ALDH1A1 protects tumor cells against various cytotoxic drugs, whereas ALDH1A3 may play an important role in progression and metastasis; both are candidate biomarkers of prognosis in many cancer types." (PMID 28253891, 2017). "Citral could reduce the proliferation of MDA-MB-231 cells by inhibiting the cancer stem cell marker ALDH1A3 (Aldehyde dehydrogenase 1 family, member A3)." (PMID 28829378, 2017). "With regard to the CAF model, patient-derived normal and according cancer-associated fibroblasts revealed a conserved gene expression, defined by increased transcript levels of ACTA2, COL1A1, TNC, VEGFA and ALDH1A3, with concomitant decreased expression of CAV1, CD44 and VIM in CAFs." (PMID 28372546, 2017). "Taken together, our results suggest that tTG may represent a novel therapeutic target for aggressive GSCs and other ALDH1+ cancer cells, as well as provide insight into the contributions of ALDH1A3 to the CSC phenotype." (PMID 28423611, 2017). "Recently, it has been reported that ALDH1A3 in particular contributes to Aldeflour high activity, which may be tissue and cancer specific, in murine HSC, murine pancreatic progenitor cells, and human breast CSCs." (PMID 26783961, 2016). "Since ALDH1A3 supports the clonogenic and tumorigenic potential of cancer stem cells, we hypothesized that it might also promote stemness in NPCs and that Sam68 exerted its effects through modulation of ALDH1A3 expression." (PMID 27845622, 2016). "In addition, we show that the transcripts of some cancer markers, such as ALDH1A3 and PTGS2, are increased at both early and late stages of tongue carcinogenesis." (PMID 26110572, 2015).
cancer (continued). "Thus, ALDH1A3 may be helpful as a predictive marker to both determine which cancers may respond to the inhibitors discovered here and which cancers may be accelerated by retinoid pathway agonists." (PMID 41210994, 2025). "Data presented here demonstrate that ALDH1A3 is expressed and predicts worse outcomes in multiple cancer types that do not respond to immune checkpoint inhibitors, suggesting that therapeutic targeting of ALDH1A3 is a compelling strategy in anti-PD-1-resistant cancers." (PMID 41210994, 2025). "Therefore, we investigated whether the senescent cells induced by the knockdown of ALDH1A3 could promote the in vitro proliferation and migration of cancers." (PMID 40227735, 2025). "This has necessitated that studies on ALDH1A3 be performed in immune-deficient models where the paracrine effects of tumor-derived atRA would not be identified, thus explaining why a clear mechanism of ALDH1A3 has not yet been identified in cancer." (PMID 41210994, 2025). "Therefore, ALDH1A3 emerges as a key player in a few “hallmarks of cancer”." (PMID 39251846, 2024). "Although the tumorigenic property of ALDH1A3 in cancer has been observed, it is suggested that upregulated epithelial-to-mesenchymal transition and cancer stem cell-like properties related genes, including ALDH13, may be involved in the lymphatic spread of papillary thyroid microcarcinoma." (PMID 35280765, 2022). "Therefore, finding selective inhibitors against ALDH1A3 could result in new treatment options for cancer treatment." (PMID 34641313, 2021). "Interestingly, one of the known fusion partners of ALDH1A3 is USP25, a ubiquitin-dependent protease, which localizes in both nucleus and cytoplasm and has been implicated as a tumor-promoting factor in different types of human cancers." (PMID 35052687, 2021). "Furthermore, since ALDH1A3 has physiological functions, targeting its key downstream cancer-specific effectors may be better tolerated than targeting ALDH1A3 directly." (PMID 31197235, 2020). "Therefore, targeting ALDH1A3 in cancer is of great interest." (PMID 32111066, 2020). "In oncology, there is no consensus on whether ALDH1A3 is a marker or a pathogenic factor in cancer progression." (PMID 27572106, 2016). "Our findings demonstrate that ALDH1A3 gene knockout accelerated the cellular senescent-like phenotype, but inhibits SASP’s promoting effect on cancer by suppressing the cGAS–STING immune pathway." (PMID 40227735, 2025). "Many studies have independently reported that ALDH1A-expressing cancers are more tumorigenic and predict worse clinical outcomes, while other studies show that ALDH1A1 and ALDH1A3 promote cardiovascular diseases or obesity." (PMID 41210994, 2025). "Increased expression of ALDH1A3 in GBM and many other cancers is now confirmed by multiple approaches by different authors." (PMID 39001459, 2024). "We observed a significant increase in the expression of cancer stem cell markers, including CD44, VEGFA, ITGB1, ALDH1A3, SOX9 and NECTIN4, and enrichment in stemness-related pathways, such as the hedgehog, PI3K-AKT-mTOR, and WNT signaling pathways." (PMID 38892065, 2024). "The migratory subtype also exhibits similar characteristics to those of cancer stem cells (CSC) with expression of known CSC markers (CD44, SOX9, ALDH1A3 and VEGFA) and those for tissue migration, angiogenesis, EMT and the TNFA pathway." (PMID 38892065, 2024). "Increased production of atRA by ALDH1A3 in GBM increases the level of transglutaminase, promoting the survival of cancer cells." (PMID 39001459, 2024). "We found that treatments enriched the expression of CSC markers CD166, ALDH1A3, CD133, and LGR5 and activated PI3K/Akt pathway in cancer cells." (PMID 37791907, 2023). "ALDH1A3 is a member of the ALDH family and is well characterized as a cancer stem cell marker in various cancers, including lung, bile duct, prostate, colon, gastric, breast, and melanoma." (PMID 37686698, 2023).